CD4 (CD4 molecule)
Diseases named in the same sentence as CD4 in open-access papers (continued):
Sharing a sentence is not in itself a finding about the gene and the disease.
tumor (continued). "However, a significantly higher percentage of interferon-gamma (IFN-γ) producing and a lower percentage of interleukin-10 (IL-10) producing CD4+ T cells derived from the spleen of tumor-bearing A. vulgaris extract treated mice were found." (PMID 38920557, 2024). "IFNγ induces anti-tumor responses through CD4+ T helper cells and CD8+ T cells." (PMID 38928150, 2024). "Compared to tumor-bearing controls, the percentage of IFNγ+ CD4+ Th1-prone cells after cryo-thermal therapy was higher than that of other CD4+ T subsets, although the increased percentages of Th1, Th17, Tfh prone CD4+ T cells were observed on day 7 after cryo-thermal therapy." (PMID 38827732, 2024). "The only lymphoid subset that can promote tumor progression is the regulatory CD4+ T lymphocyte subset (Treg), which directly secretes or facilitates the formation of immunosuppressive molecules (e.g., IL-10, adenosine) and modulates the APC function (e.g., via CTLA-4–CD80/86 interactions)." (PMID 38542199, 2024). "Moreover, CD4+ T cells license dendritic cells (DCs) to activate CD8+ cells by either cross-presenting tumor antigens to CD8+ T cells or inducing the production of cytokines and costimulatory molecules." (PMID 38444857, 2024). "However, the observed early-onset pseudoprogression, as well as a positive proximity ligation assay, suggest a relevant and functional CD4+ T cell response in vivo against the primary tumor presenting the neoepitope H3K27M on HLA-DR molecules." (PMID 38306431, 2024). "By secreting IL-2, TNFα, and IFN-γ, Th1-polarized CD4+ T cells play a relevant role in anti-tumor immunity, including in NMSCs, and may predicate the success of anti-cancer immune therapy." (PMID 38891095, 2024). "Bilateral subcutaneous tumor tissues were removed on day 14 of treatment, and immunohistochemistry for CD-4 and CD-8 was performed to compare the number of positive cells per unit area between the ICG-Lipo-PTX and PDT-only groups on the PDT and non-PDT sides (n = 4 per group)." (PMID 38515576, 2024). "Furthermore, we found that the GAS7 expression was positively related to the infiltration of CD8 T cells, B cells, macrophages, CD4 T cells, neutrophils and Dendritic cells in the tumor microenvironment of NSCLC patients." (PMID 38370374, 2024). "Furthermore, Foxp3+ CD25+ CD4+ T cells (Treg), defined as a suppressor in aberrant immune response, also play a role in the suppression of anti-tumor immunity." (PMID 38164171, 2024). "Administration of agonistic anti-GITR mAb in murine glioblastoma was observed to promote the differentiation of Tregs into CD4 Teffs cells, alleviate the Treg-mediated suppression of the anti-tumor immune response and induce the generation of potent anti-tumor effector cells." (PMID 38891091, 2024). "The paradoxical effect of tumor-intrinsic EZH2 knockout on infiltrated neutrophils (decrease) as well as CD4+ and CD8+ T cells (increase) was even more striking when expressed as ratios, revealing a >20-fold decrease in the neutrophil:CD8+ T-cell ratio in EZH2 KO vs. WT and EZH2 OE tumors." (PMID 38791429, 2024). "completely removes the need to identify potentially immunogenic tumor-associated antigens as targets for generation of de novo CD8+ and helper CD4+ T cell responses; and 4) leads to potent T cell-mediated rejection of aggressive, immunologically cold, non-immunogenic tumors." (PMID 39606441, 2024). "For microenvironment analysis, the proportion of effector memory T cells was increased and the better treatment efficacy may be attributed to the elevated effector memory CD4 + T cells within the tumor." (PMID 38630135, 2024). "Age, smoking history, and stage showed very limited effect on the expression level differences of tumor immune microenvironmental related markers, whereas female patients had significantly both higher CD4 positive cell density score (p = 0.002) than male patients." (PMID 38899854, 2024).
tumor (continued). "Furthermore, targeting CD47 is demonstrated to promote tumor vascular normalization through the heightened infiltration of CD4+ T cells." (PMID 38398223, 2024). "Moreover, CD4+ T cells indirectly influence the function of CD8+ T cells within the tumor microenvironment through cytokine secretion and immune regulation." (PMID 38791916, 2024). "The spatial landscape that mixes distributed patterns among Tregs, tumor cells, CD4+T cells, and CD8+T cells were underscored to help in the stratification of patients who might be at risk of early recurrence." (PMID 39093404, 2024). "In addition, the density of regulatory CD4+ T cells in the tumor center is predominant over those in the invasive margin; however, the difference was not statistically significant." (PMID 38674427, 2024). "For instance, B. fragilis can exert beneficial effects, including increased CD4+ T cells on the host immune system, which may improve anti-tumor immunity." (PMID 38547865, 2024). "Furthermore, analysis of cDC2-deficient mice showed that cDC2 derived from tumor tissues enhances the ability of cDC1 to induce tumor-specific CTLs through the activation of CD4+ T cells in TdLNs." (PMID 39206204, 2024). "Furthermore, our study substantiates that anti-CD47 Ab contributes to tumor vascular normalization by enhancing CD4+ T cell infiltration, highlighting the role of tumor vascular normalization in the anti-tumor effect of CD47 targeting." (PMID 38398223, 2024). "Despite numerous conflicting reports on the impact of CD4 + Th1 cells on the survival outcomes of PDAC patients, mechanistically, these cells are linked with key cytokines IL-2, IFN-γ, and TNF-α, contributing to anti-tumor immunity." (PMID 38833018, 2024). "However, tumor-bearing CD11c:DTA mice exhibited a reduced proportion of CD4+Foxp3+ Treg cells and Teff cells in TdLNs." (PMID 39206204, 2024). "Recent research highlights the potential of ectopically expressed LMP1 in tumor B cells to prime autologous CD4+ T-cells (LMP1-CD4+ T) against a wide array of endogenous tumor antigens, including TAAs and neoantigens, suggesting efficient treatment for B cell malignancies." (PMID 39075601, 2024). "Moreover, the accumulation of lactate within the tumor microenvironment can inhibit the proliferation and functionality of CD4+ T cells, concurrently fostering the differentiation of Tregs." (PMID 39676861, 2024). "Additionally, transferred CD4+ T cells can effectively regulate tumor growth, either in isolation or through collaborative interactions with other immune cell populations." (PMID 38426090, 2024). "Treatment with sialyltransferase inhibitor (SI) could partially reverse the inhibitory effect of tumor-conditioned MSCs on CD4 and CD8 cell proliferation." (PMID 39727942, 2024). "CD4+ Tregs express high-affinity IL-2 receptors and expand in response to IL-2, which may limit the anti-tumor activity of activated CD8+ T cells." (PMID 38928238, 2024). "We then compared the extent of immune infiltration among consistent and disagreeing measurements and found an association of the discordant individual tumor with the presence of an immune infiltration (p = 0.04 for CD8 infiltration, p = 0.05 for CD4 infiltration)." (PMID 38289494, 2024). "To determine whether C5aR deficiency conferred better tumor control depending on enhanced T cell responses, we depleted CD8+ T cells or CD4+ T cells in C5aR−/− tumor-bearing mice with anti-CD8 or anti-CD4 antibodies." (PMID 38098230, 2024). "Importantly, anti-tumor lymphocytes, CD4+ and CD8+ T-cells, were decreased in LvMs and NLvMs compared to BrT but increased in AxMs and NAxLNMs." (PMID 38643348, 2024).
tumor (continued). "Furthermore, factors such as age, gender, CD4 cell count, tumor type, tumor size, and location of the tumor had a noticeable impact on the outcome in HIV-related EBV-SMTs." (PMID 39781121, 2024). "Notably, both animal work and human data revealed a minimal effect of LFA-1 on the tumor-specific trafficking of other CD4+ T cell subsets, indicating specificity in mediating Treg recruitment." (PMID 38787791, 2024). "In addition, the combination of anti‐PD‐1 and B. bifidum increased the levels of cytokine‐producing IFN‐γ+CD8+ and IL‐2+CD4+ tumor‐infiltrating T cells in a peptidoglycan‐dependent manner." (PMID 39031507, 2024). "Additionally, Mn has been observed to enhance the infiltration of CD8+ and CD4+ T cells into tumors, underscoring its essential role in maintaining the host’s anti-tumor immune response." (PMID 39050748, 2024). "As RocA increased tumor-infiltrating CD4+ and CD8+ T cells, we next investigated whether these TILs were functional in tumor microenvironment." (PMID 38833034, 2024). "The differences of neoantigen burden and tumor immune microenvironmental features, especially CD4+ T cell composition and function, between female and males may be the potential biological explanation and worthy of further investigation." (PMID 38899854, 2024). "Moreover, among tumor infiltrating CD4+ T cell subsets IL32β is expressed at highest amounts by suppressive Treg and Th1 Teff." (PMID 39211051, 2024). "Additionally, increased levels of CD4+CD25high regulatory T (Treg) cells, known for their potent immunosuppressive effects, were observed in both the blood and tumor tissue of early-stage PCa patients." (PMID 38888513, 2024). "These promising therapeutic data may result not only from the selective and efficient direct killing effect on those malignant CD4 cells but also from the induction of systemic anti-tumor immunity." (PMID 38931936, 2024). "Furthermore, we found that the proportion within the tumor-draining lymph nodes of both Tbet-expressing CD4+ T cells and Treg was significantly lowered in response to the combination of treatment when compared to controls or PD-1 blockade alone." (PMID 38385162, 2024). "To determine the role of PGE2 in tumour escape from anticancer T cell responses, we generated Cd4crePtger2−/−Ptger4fl/fl mice in which Cre recombinase activity induces the deletion of EP4 in CD4+ and CD8+ T cells on a global EP2-deficient background." (PMID 38658748, 2024). "The tumor size and weight were also larger in mice with anti‐CD4 treatment." (PMID 39225354, 2024). "The surface of TAMs also express MHC-II, which presented tumor antigens to CD4+ T cells." (PMID 39654892, 2024). "However, our results suggest that the presence of naive CD4+ T cells is a protective factor for HCC, suggesting that the differentiation of naive CD4+ cells has a certain tendency in the immune environment of HCC tumours." (PMID 39816386, 2024). "The primary anti-tumor immune cells in this environment are CD4+ and CD8+ T cells." (PMID 39372398, 2024). "Furthermore, targeting CD47 was validated to promote the normalization of tumor vasculature by increasing the infiltration of CD4+ T cells." (PMID 38398223, 2024). "Increases in the numbers of tumor infiltrating CD4+T and CD8+T cells were observed after treatment." (PMID 38516270, 2024). "Alternatively, the marked cytotoxic attack against tumor cells leads to the exposure of numerous host antigens and the potential generation of autoreactive CD4+/CD8+ T cells that target cross-reactive dermal/epidermal self-antigens, which have not yet been identified." (PMID 38541099, 2024). "Moreover, the rank of intestinal CD4+ α/β T cells was positively correlated (Pearson’s r = 0.72, P = 0.0016) with an independent measure of tumor fraction in cfDNA (ichorCNA31)." (PMID 38472221, 2024).
tumor (continued). "Thus, our data highlight the difference in the lymphoid cell TME between the investigated tumor entities, indicating a low lymphoid cell infiltration into KP tumors, but a strong skew towards CD4+ T cell infiltration." (PMID 38254785, 2024). "CD4+ T helper 1 (Th-1) cells also mediate an anti-tumor response through the secretion of proinflammatory cytokines such as IL-2, TNF⍺, and IFN-γ, which promotes not only T-cell priming and CTL cytotoxicity but also the anti-tumoral activity of macrophages and NK cells." (PMID 38254796, 2024). "NK cells are among the early responders, and by lysing cancer cells, they expose tumor antigens to the care of DCs, which present them to T-cells in tumor-draining lymph nodes to induce polarization of CD4 T-cells into Th1 helper cells and the conversion of CD8 T-cells into cytotoxic T-cells (CTL)." (PMID 39511139, 2024). "CD4+ Th17 cells also play unclear roles in the tumour immune response." (PMID 38468489, 2024). "Importantly, the WT134‐51 helper peptide, which can be utilized for all MHC class II types, significantly contributes to tumor eradication not only through CD4+ Th1 cells, but also WT1-specific CD8+ CTLs in antitumor immunity." (PMID 39737308, 2024). "The functional relevance of Ly6C(+)CD4(+) T cells in the context of anti-tumor activity in our study remains unknown at this stage." (PMID 38895115, 2024). "We therefore established a sorting strategy in which we removed T cells from the tumour-specific CD4+ T cell population that expressed genes of surface markers not found in cluster 3 cells (that is, Cd25, Cd200 and Cd153), and positively sorted the remaining cells for CD39 expression." (PMID 39048822, 2024). "Notably, it was reported recently that GBM stimulates tumor-infiltrating CD4+ T cells to shift towards the Th17 phenotype." (PMID 38786032, 2024). "The anti-tumor ability of CD4+ T cells has been widely demonstrated in mouse models and humans." (PMID 38953025, 2024). "Furthermore, neoantigens are displayed by both HLA-I and HLA-II molecules, and neoantigen-reactive CD4+ T cells are likely to play an indispensable role in T cell–mediated tumor rejection in vivo." (PMID 39292790, 2024). "Alongside this, baicalin could improve the anti-tumor immune function, down-regulating PD-L1 expression and upregulating the CD4+ and CD8+ T cell ratio, thereby improving the tumor immune microenvironmen." (PMID 38783955, 2024). "Notably, the signature of tumor-infiltrating dysfunctional T cells was also enriched in VAT-derived PD-1+CD4 Tconv cells from OB-Dys." (PMID 38380252, 2024). "Importantly, some tumors assigned as immune-excluded immunotypes, based on CD8+T cell densities, displayed CD4+T helper cell infiltration into the tumor center (P12, P16)." (PMID 39053947, 2024). "CD4 + T helper cells also participate in anti‐tumour immunity through a variety of mechanisms." (PMID 39187946, 2024). "Moreover, the expression of 24 disulfidptosis-related genes (DRGs) was significantly different in different tumor-infiltrating immune cells, and most DRGs were expressed at low levels in CD4+ regulatory T cells and plasma cells." (PMID 39091494, 2024). "Furthermore, the numbers of regulatory T cells (Tregs; IFN-γ−Foxp3+) within the tumor-infiltrating CD4+ T-cell population were dramatically reduced in the combination group." (PMID 38307859, 2024). "The intratumoral CD4+/CD8 + ratio was significantly different in the SCC tumor subtype." (PMID 38468248, 2024). "The preferential enrichment of mast cells activated and T cells CD4 memory activated versus the preferential depletion of mast cells resting and T cells CD4 resting suggested that tumorigenesis activates resting immune cell-types, potentiating their infiltration of the tumor microenvironment." (PMID 39484215, 2024). "CD4+T cells promote anti-tumor immunity directly or indirectly through the help of CD8+T cells." (PMID 38550587, 2024).
tumor (continued). "TIM-3+CD4 T cells may represent functional regulatory T cells that contribute to the formation of immunosuppressive tumor microenvironments." (PMID 39206199, 2024). "The cytotoxic effect of CD4+ and CD8+ T-lymphocytes was caused by the induction of apoptotic and necroptotic processes in tumor cells after the interaction of the FasL lymphocyte with the Fas receptor of the tumor cell." (PMID 38203798, 2024). "Complete tumour elimination, especially in patients with late-stage metastatic lesions, requires the recruitment of an antigen-dependent immune response through collaboration between CD4+/CD8+ T cells and B cells, as well as the production of cytokines." (PMID 38279262, 2024). "The results of anti-CD4 and CD8 staining of tumor tissues demonstrated that compared with the PBS and DTT control group, inoculation of DTT-EG3, DTT-EG5, DTT-EG6, and DTT-EG7 vaccines led to a significant increase in the proportion of CD4+ T cells in tumor tissues." (PMID 39766327, 2024). "It was also assessed how CD8+ and CD4+ T lymphocytes identify distinct tumor antigens." (PMID 38672570, 2024). "We hypothesize that tumor-expressing HVEM can inhibit the proliferation of CD4+ T cells in vitro and that HVEM gene expression is a prognostic biomarker upregulated in ALL." (PMID 38785930, 2024). "Reciprocally, HPV+ tumor cells could directly interact with CD4+T cells and activate CD4_C3_CXCL13 T cell differentiation, which also had elevated secretion of IFNγ." (PMID 39105803, 2024). "Consequently, significant score differences between tumor and normal samples were observed within two disulfidptosis-related CD4+ T cell subgroups, namely, DSTN+CD4T-C1 and FLNA+CD4T-C2." (PMID 38292868, 2024). "A subset of CD4+ T cells can acquire cytolytic function towards MHC-II-expressing tumor cells." (PMID 39544936, 2024). "The efficient eradication of tumor cells heavily relies on the presence of CD4+ T cells." (PMID 38791916, 2024). "Meanwhile, the anti-tumor response of CD8+ T cells is largely enhanced by CD4+ T cells." (PMID 38673829, 2024). "Indeed, at least certain DC subsets are competent to cross-present tumor antigens acquired from phagocytosed tumor cells for presentation to antitumor and antiviral CD4+ and CDS’ T cells." (PMID 38927447, 2024). "Additionally, another one cluster in tumor region the was characterized by lymphocytes and immune inhibitory markers (including CD4, CD8, NK, NKT, B cells, memory T, LAG3, TIM3, CTLA4, IDO and PD-1)." (PMID 38373959, 2024). "Tumor cell clonality is related to the polarization of CD4 T cells and CD8 T cells: memory and cytotoxic CD8 T cells are enriched in low clonality groups, while proliferative pre-exhausted and conventional pre-exhausted T cells are enriched in high clonality groups." (PMID 39156971, 2024). "Notably, CXCL13 and PD-1 were also detected in some of the IFNβ-expressing CD4+ T-cell clusters in both tumor types." (PMID 38383773, 2024). "CD4+/CD8+ T cell depletion led to full rescue of Mgat5-KO tumor growth." (PMID 38912584, 2024). "Moreover, patients treated with SBRT have demonstrated a significant reduction in the distribution of CD8+/CD4+ T cells within the tumor as well as a substantial reduction in the number of perivascular CD8+ T cells." (PMID 38434964, 2024). "Nevertheless, compared with the sole use of Sor, the co-administration of PF and Sor in tumor-bearing mice significantly enhanced the infiltration of CD4+ T cells in tumor tissues, while reversing the inhibition of CD8+ T cell infiltration and reversing the IL-2 depletion induced by Sor." (PMID 38312647, 2024). "This approach has been employed in studies targeting tumor cells via tumor-associated antigens such as HER2, EGFR, and EpCAM or immune cells through immunological receptors like CD20, CD19, CD8, CD4, and CD30." (PMID 39772246, 2024). "CD4 cells are extensively recognized for their anti-tumor immune function in the TME." (PMID 38672263, 2024).